ARID1A (AT-rich interaction domain 1A)
Diseases named in the same sentence as ARID1A in open-access papers (continued):
Sharing a sentence is not in itself a finding about the gene and the disease.
ovarian tumors (29 papers, 2013 to 2025). "They correlated the status of ARID1A with the immunohistochemistry and found a significant correlation of ARID1A expression with its mutational status in 51 out of 56 ovarian tumors." (PMID 31126056, 2019). "Treatment with anti-PD-L1 antibody reduced tumor burden leading to prolonged survival of these mice bearing ARID1A-deficient ovarian tumors as compared to mice bearing ARID1A wild type ovarian tumors." (PMID 31731647, 2019). "Clear cell cancer and low grade endometrioid are major types of ovarian tumors classified as Type I malignancies with mutations in ARID1A (AT-rich interactive domain-containing protein 1A), K-Ras (Kirsten rat sarcoma) and PTEN (phosphatase and tensin homolog)." (PMID 30231564, 2018). "Moreover, in ARID1A-deficient OCCC, EZH2 methyltransferase inhibitors have been reported to act in a synthetically lethal manner, causing ARID1A-mutant ovarian tumors to be regressed in tumor-bearing mice." (PMID 34671561, 2021). "PIK3CA and ARID1A mutations were more frequent in clear cell or endometrioid tumors than in other types (6/7 vs. 4/15 and 4/7 vs. 3/15; P = 0.016 and 0.11, respectively), consistent with previous studies of all-age-group ovarian tumors." (PMID 29464067, 2018). "Interestingly, ARID1A mutations frequently co-occur with PIK3CA or PTEN mutations in human tumors, and double mutations of Arid1a with Pten or Pik3ca result in ovarian tumor formation in mice suggesting a cooperative carcinogenic role of PI3K and chromatin remodeling pathways." (PMID 31481116, 2019). "And ARID1A-deficient mice combined with anti-PD-L1 treatment were significantly more effective than mice with ARID1A wild-type ovarian tumors." (PMID 36685594, 2022). "ABT263 is sufficient to overcome resistance to an EZH2 inhibitor and synergizes with an EZH2 inhibitor in vivo in ARID1A-inactivated ovarian tumor mouse models." (PMID 30297712, 2018). "In an animal model, mice with both ARID1A homozygous deletion and H104R activating mutation of PIK3CA in ovarian surface epithelium rapidly developed ovarian tumours with haemorrhagic ascites and peritoneal metastases, whereas those with ARID1A deletion or PIK3CA mutations alone did not." (PMID 38275587, 2023). "In contrast, treatment with anti‐PD‐L1 antibody reduced the tumour burden and prolonged the survival of mice bearing an Arid1a deficiency but not ARID1A wild‐type ovarian tumours." (PMID 32162380, 2020). "Mutations of ARID1A seem to be frequently involved in ERONs, and almost 73% of heterozygous mutated ovarian tumors are characterized by a loss of protein expression without the loss of heterozygosity." (PMID 31126056, 2019). "In addition, ABT263 synergizes with an EZH2 inhibitor in vivo in ARID1A-inactivated ovarian tumor mouse models." (PMID 30297712, 2018). "Endometriosis-related ovarian neoplasms (ERONs) have recently attracted considerable attention; however, the prevalence and patterns of ARID1A and POLE mutations in ERONs have not been studied in detail." (PMID 29599905, 2018). "However, 40% of the mice with a simultaneous knock-out of ARID1A and PTEN developed poorly differentiated ovarian tumors, and 60% developed ovarian epithelium hyperplasia." (PMID 31126056, 2019). "In this study, we also demonstrated that negative expression of ARID1A was common in clear cell (63.6%) and endometrioid (19%) ovarian tumors as well as clear cell (100%) and endometrioid (89.8%) uterine cancer." (PMID 29451900, 2018). "Co-immunoprecipitation (coIP) analysis demonstrated an interaction between EZH2 and HDAC2 in ARID1A-mutated Ovarian Tumor-derived Cell Line 21G (TOV21G), and the restoration of wild-type ARID1A disrupted this interaction, suggesting that EZH2 did not interact with HDAC2 in ARID1A wild-type cells." (PMID 38794190, 2024).
ovarian endometrioid carcinoma (26 papers, 2012 to 2025). "Another paper confirmed that the loss of ARID1A expression, a surrogate for ARID1A mutations, has been reported in one-third of these tumors, a frequency similar to that seen in ovarian endometrioid carcinomas, supporting their close relationship." (PMID 35621684, 2022). "Other tumors harboring ARID1A mutations are uterine endometrioid carcinoma (47–60%), ovarian endometrioid carcinoma (30%), gastric cancer (29%), colorectal cancer (5–10%), and pancreatic cancer (3–5%)." (PMID 34070839, 2021). "Previously it has been reported that about 30% of Caucasians, 25% of Asians and 10% of Pacific Islanders exhibited loss of ARID1A expression in clear cell and endometrioid ovarian carcinoma." (PMID 34924820, 2021). "Ovarian endometrioid carcinomas are characterized by frequent somatic ARID1A inactivating mutations (30-55% of cases)." (PMID 27231561, 2015). "In addition, as described in Materials and Methods (“patient’s clinical history”), a Q1346* mutation in ARID1A, which is often mutated in clear cell and endometrioid ovarian carcinomas, was identified by FoundationOne® CDx testing of tumour tissue." (PMID 38573494, 2024). "ARID1A is mutated in over 50% of OCCCs and 30% of ovarian endometrioid carcinomas." (PMID 34070839, 2021). "Combination of inactivation of ARID1A with activation of PIK3CA activates the development of ovarian endometrioid carcinoma." (PMID 35070505, 2022). "ARID1A positive staining and simultaneous ß-Catenin n-m+ staining were mostly seen in endometrioid ovarian carcinoma and the tumors belonged mostly to FIGO staging I." (PMID 29451900, 2018). "Co-occurrence of mutations in ARID1A and PTEN have been shown as potential cancer driving mutations in endometrioid ovarian carcinomas in animal models." (PMID 28103826, 2017). "Inactivating mutations of ARID1A and loss of its expression was found especially in endometrium-derived tumors, including ovarian CCC, ovarian endometrioid carcinomas and EC." (PMID 25885815, 2015). "ARID1A loss was, however, shown to be associated with mismatch repair deficiency and increased CD8+ tumour infiltrating lymphocytes in endometrioid ovarian carcinoma, which may be relevant for future studies." (PMID 35647895, 2022). "When Pten is combined with Arid1a loss, mice develop endometrioid ovarian carcinoma rather than HGSC34." (PMID 29042553, 2017). "We evaluated both WES and WGS data for homozygous deletions and identified losses in multiple genes known to be altered in ovarian endometrioid carcinomas, including PTEN, NF1, ARID1A, BRCA1, and others." (PMID 40981433, 2025). "Activation of oncogenic KRAS and PIK3CA pathways and inactivation of tumor suppressor genes, ARID1A and PTEN, are observed in clear cell and endometrioid ovarian carcinomas, respectively." (PMID 34454550, 2021). "It has been demonstrated in a genetically engineered mouse model that co-deletion of ARID1A and PTEN results in the formation of ovarian carcinoma with morphological and molecular features resembling human ovarian endometrioid carcinoma." (PMID 27231561, 2015). "This is illustrated e.g. by the SNVs in PTEN (p.Cys124Ser and p.Ala126Thr) and ARID1A (p.Arg1053fs) which were found in both, the endometrial and the ovarian endometrioid carcinoma, but were not conserved in the distant lung metastasis." (PMID 28103826, 2017).
cervical cancer (25 papers, 2015 to 2025). A primary or metastatic malignant neoplasm involving the cervix. "Accumulating studies have identified various genomic mutations of PIK3CA, EP300, FBXW7, PTEN, HLA-A, ARID1A and so on in different cervical cancer tissues." (PMID 32123519, 2020). "ARID1A and B2M mutations may serve as potential biomarkers for predicting treatment outcomes in cervical cancer patients undergoing dCRT." (PMID 40536270, 2025). "Decreased chromatin accessibility has also been observed for other cancer types such as colon and cervical cancer, arguing for a context‐independent function of ARID1A." (PMID 40170512, 2025). "MiR-144-3p downregulates ARID1A and thus promotes cell proliferation, metastasis, and Sunitinib resistance in clear cell renal cell carcinoma, whereas miR-31 functions as an oncomir for ARID1A in cervical cancer." (PMID 39796161, 2025). "MiR-221 and miR-222 simultaneously target ARID1A and enhance the proliferation and invasion of cervical cancer cells." (PMID 39796161, 2025). "For example, a unique set of endometrial-like cervical cancers, comprised predominantly of HPV-negative tumors, were reported with relatively high frequencies of KRAS, ARID1A, and PTEN mutations." (PMID 38067297, 2023). "The present study is the first to report an association between ARID1A mutations and high TMB status in cervical cancer." (PMID 36831552, 2023). "The Cancer Genome Atlas (TCGA) Research Network has identified high frequencies of ARID1A, KRAS, and PTEN mutations in endometrial-like cervical cancers." (PMID 36397138, 2022). "Here, we interrogate the impact of siRNA knockdown of ARID1a compared to a functional interference approach in the HeLa human cervical cancer cell line." (PMID 36344675, 2022). "A set of endometrial-like cervical cancers comprised predominantly of HPV-negative tumors and characterized by mutations in KRAS, ARID1A and PTEN was discovered in another study." (PMID 33736612, 2021). "These authors also implied that miR-31 plays an important role in the regulation of cervical cancer’s malignant behavior, including cell proliferation and invasion, by directly targeting ARID1A." (PMID 33803022, 2021). "These pathways and the recurrently mutated genes involved therein, such as EP300, ARID1A, FBXW7, NFE2L2, PIK3CA, and ERBB2, were all found to be pathogenic in previous cervical cancer studies." (PMID 28390392, 2017). "Besides, miR-222 was proved to target ARID1A to enhance proliferation and invasion of cervical cancer cells." (PMID 31273056, 2019). "Chromatin remodeling genes ARID1A and ARID5B, WNT signaling regulator CTNNB1, and the negative regulator of PI3K signaling PTEN, were among the notable genes significantly more mutated in HPV-inactive cervical cancers." (PMID 28077784, 2017). "Furthermore, EP300, ARID1A, FBXW7, NFE2L2, PIK3CA, and ERBB2 have all been previously reported as pathogenic genes in cervical cancer, and we highlighted the roles of MLL2, MLL3, and CREBBP in the tumorigenesis." (PMID 28390392, 2017). "One recent study of 228 cervical cancers using TCGA data identified SHKBP1, ERBB3, CASP8, HLA-A, and TGFBR2 as novel significantly mutated genes, and previously identified pathogenic genes including PIK3CA, EP300, ARID1A, and NFE2L2 were also confirmed." (PMID 28390392, 2017). "Another study in 15 cervical cancer patients from Hong Kong revealed frequently altered genes, including FAT1, ARID1A, ERBB2, and PIK3CA." (PMID 28390392, 2017).
cervical cancer (continued). "In this study, we observed that Arid1a exhibits a statistically significant downregulation both in endometrial and vulvar cancer patients, but not in cervical cancer patients." (PMID 26559525, 2015).
serous ovarian carcinomas (25 papers, 2011 to 2025). "ARID1A mutations, although uncommon in high-grade serous carcinoma of the ovary, are relatively common in cancers with clear cell and endometrioid histology." (PMID 36910637, 2023). "In support, we found that ARID1A loss was linked to poor outcome in TCGA high-grade serous ovarian cancers (TCGA HGSOCs) receiving platinum as the standard of care (p = 0.01)." (PMID 29669295, 2018). "Additionally, the combination of AZD6738 (ATR inhibitor) and olaparib (inhibitor of PARP (Poly ADP-ribose polymerase)) reduced tumor burden in BRCA-mutant high grade serous ovarian cancer although other study showed ARID1A loss is associated with PARP inhibitor resistance." (PMID 37087441, 2023). "In an investigation about ARID1A mutations, they were found in 46% of ovarian CCCs and 30% of ECs but not in high-grade serous ovarian carcinomas." (PMID 40364006, 2025). "This may explain the paradox of why tumours with high genomic instability, such as high-grade serous ovarian carcinoma (HGSOC), have a low prevalence of ARID1A, as loss of the ARID1A-BAF complex would render these tumours non-viable." (PMID 38275587, 2023). "Both subtypes of serous ovarian carcinoma, a mesonephric adenocarcinoma case and the small cell carcinomas of the ovary, hypercalcaemic type, were ARID1A wild‐type and showed high protein expression (with scores ranging between 11 and 12 (EPR13501), 11 and 12 (D2A8U) and 6 and 12 (HPA005456)." (PMID 29659191, 2018). "They report a similar prevalence of ARID1A loss to published studies, with loss of ARID1A staining observed in 25% of ENOC and 42% of CCOCs, with retention of ARID1A protein in more than 95% of both low‐grade (n = 111) and high‐grade serous ovarian cancer cases (n = 2,548)." (PMID 35647895, 2022). "First, signature genes characteristic of the tumor types in question, such as APC in colorectal tumors and ARID1A, PIK3CA, and PTEN in non-serous ovarian carcinomas were well represented." (PMID 29296220, 2017). "In addition, this panel is targeting “hotspot” region of genes that are frequently mutated in human cancer thus other infrequently altered genes but of significance to serous ovarian cancers might have been excluded such as ARID1A, BRCA1, BRCA2, CSMD3, NF1, CDK12, FAT3 and GABRA6." (PMID 25404506, 2014).
Coffin-Siris syndrome (21 papers, 2015 to 2024). "We describe two cases with confirmed Coffin–Siris syndrome, and mutations in the ARID1A gene were found in both cases." (PMID 36540875, 2022). "The current EpiSignTM BAFopathy episignature encompasses several subtypes of Coffin–Siris syndrome associated with multiple genes (ARID1A, ARID1B, SMARCB1, SMARCA4) and Nicolaides–Baraitser syndrome (SMARCA2)." (PMID 36430143, 2022). "We describe two cases with Coffin–Siris syndrome with mutations in the ARID1A gene, with dissimilar presentation and clinical course." (PMID 36540875, 2022). "Mutations in AT‐rich interactive domain‐containing protein 1A (ARID1A) cause Coffin‐Siris syndrome (CSS), a rare genetic disorder that results in mild to severe intellectual disabilities." (PMID 36385502, 2022). "In particular, proband 19 carried a p.D2155N (c.6463G>A) variant in TRIO, a gene which has been associated with ASD and ID, and proband 18 carried a deletion of five amino acids (c.1029_1043del, p.Ala345_Ala349del) in ARID1A, one of the causal genes for Coffin–Siris syndrome." (PMID 29463886, 2019). "High frequency of ARID1A mutations have been reported in Coffin-Siris syndrome (CSS) a congenital disorder associated with intellectual disability or developmental delay, hypoplastic fifth fingernails, and patterning defects in the head and heart." (PMID 30760980, 2019). "Here, we present two prenatal Coffin-Siris syndrome cases with autosomal dominant pathogenic variants: SMARCB1 gene c.1066_1067del, p.(Leu356AspfsTer4) variant, and a novel ARID1A gene c.1920+3_1920+6del variant." (PMID 37981638, 2024). "Coffin-Siris syndrome is caused by pathogenic variants in 12 different genes including SMARCB1 and ARID1A." (PMID 37981638, 2024). "Mutations in ARID1A and ARID1B are also an important cause of Coffin-Siris Syndrome (CSS; OMIM 135900), a rare autosomal-dominant neurodevelopmental syndrome." (PMID 35615272, 2022). "Mutations in 4 different SWI/SNF subunits including ARID1A/B were identified in three congenital syndromes that include both neural and cardiac defects: Coffin-Siris syndrome (CSS), Nicolaides-Baraitser syndrome (NCBRS), and ARID1B-related intellectual disability (ID) syndrome." (PMID 32646524, 2020). "Collectively, our results demonstrate a critical role for ARID1A in the development of microglia and neuronal differentiation, which provides insights into the genetic basis and potential therapeutic interventions of ARID1A‐related intellectual disabilities such as Coffin–Siris syndrome." (PMID 35854653, 2022). "Mutations in other genes involved with the SWI/SNF complex such as ARID1A, SMARCA2, SMARCA4, SMARCB1 and SMARCE1 are also responsible for Coffin-Siris syndrome." (PMID 26376624, 2015). "Sequence variants in other BAF complex genes are associated with other neurodevelopmental disorders including SMARCC1/2, PBRM1, ARID1A/B and SMARCA4 in ASD, PBRM1 and ARID1B in schizophrenia, SMARCB1 in Kleefstra syndrome, and ARID1A/B, SMARCA4, SMARCB1, and SMARCE1 Coffin-Siris syndrome (CSS)." (PMID 31288860, 2019). "ARID1A encodes a member of the SWItch/Sucrose NonFermenting (SWI/SNF) complex; variants in genes encoding the components of the SWI/SNF complex result in Coffin-Siris syndrome, a syndromic form of intellectual disability frequently associated with agenesis or hypoplasia of the corpus callosum." (PMID 35885948, 2022).